CCNB1 (cyclin B1)
Diseases named in the same sentence as CCNB1 in open-access papers (continued):
Sharing a sentence is not in itself a finding about the gene and the disease.
Cirrhosis (4 papers, 2012 to 2024). A chronic disorder of the liver in which liver tissue becomes scarred and is partially replaced by regenerative nodules and fibrotic tissue resulting in loss of liver function. "Cirrhosis and serum albumin were proven to have a tight relation with CCNB1's expression." (PMID 34337056, 2021). "The same study also identified CCNB1 and CCNB2 as DEGs and pathologically related to cirrhosis and serum albumin." (PMID 39452074, 2024).
diabetes (4 papers, 2014 to 2023). "It was found that hyperglycaemia remarkably increased the expression of MAD2B and accumulation of cyclin B1 in cortices of diabetes mellitus rat model and in cultured primary neurons." (PMID 24444371, 2014). "The relationship between dyslipidemia and diabetes may be as follows: LDL cholesterol decreases the expression of cyclin B1 in pancreatic β-cells and inhibits insulin secretion mediated by the LDL receptor, resulting in insulin resistance." (PMID 35992095, 2022). "Novel targets include MYO18A, SEC16A, CCNB1, MAD2L1, hsa-mir-4315, hsa-mir-6134, hsa-mir-9500, KIFC3, FBL (fibrillarin), TUBA1A and GFI1B might have crucial biologic functions in the pathogenesis of patients with diabetes mellitus and obesity." (PMID 36837510, 2023).
endometriosis (4 papers, 2009 to 2024). The growth of functional endometrial tissue in anatomic sites outside the uterine body. "Comparative studies involving cervical epithelium from women with and without moderate or severe endometriosis reveal elevated expression of genes associated with endometriosis, including cyclin B1 (CCNB1) and cyclin G1 (CCNG1)." (PMID 38398227, 2024). "Research suggests these substances induce cyclin B1 overexpression, establishing a crucial cause-and-effect sequence in endometriosis pathogenesis." (PMID 38398227, 2024). "This suggests that in the pathomechanism of endometriosis, cyclin B1’s function is complemented by the overexpression of cyclin B2." (PMID 38398227, 2024). "Evidence supporting cyclin B1 overexpression in endometriosis includes elevated levels of specific substances." (PMID 38398227, 2024). "Immunohistochemical staining has pinpointed specific locations of excessive cyclin B1 accumulation within the cell nucleus, correlating with the heightened proliferation of endometriosis cells." (PMID 38398227, 2024). "In contrast, in endometriosis tissue, genes such as CDC20, CCNB1, and CCNB2 played a central role." (PMID 38398227, 2024).
Hyperglycemia (4 papers, 2012 to 2025). An increased concentration of glucose in the blood. "Interestingly, in neurons with MAD2B shRNA, the expression of cyclin B1 induced by high glucose was also significantly reduced, implying that MAD2B deficiency prevents hyperglycaemia-induced cyclin B1 expression." (PMID 24444371, 2014). "The increased expression of CCNB1 under HG conditions implies the significant involvement of this protein in the abnormal reaction of trophoblasts to hyperglycemia." (PMID 39822992, 2025). "To understand the mechanism responsible for cyclin B1 accumulation in neurons treated with hyperglycaemia, we focused on MAD2B." (PMID 24444371, 2014). "Western blot analyses confirmed that hyperglycaemia promoted cyclin B1 accumulation in cultured neurons." (PMID 24444371, 2014). "We deduced that MAD2B mediated neuron injury induced by hyperglycaemia mainly through regulating cyclin B1." (PMID 24444371, 2014). "Then cyclin B1 protein levels were investigated in hyperglycaemia-treated neurons." (PMID 24444371, 2014). "The possible mechanism may be that hyperglycaemia-induced MAD2B expression leads to cyclin B1 accumulation, and then resulting in neuron re-entering S phase and apoptosis." (PMID 24444371, 2014). "In the present study we detected the expression of cyclin B1 under hyperglycaemia in vitro neurons." (PMID 24444371, 2014). "In summary, we demonstrated that hyperglycaemia induced the expression of MAD2B, which resulted in cyclin B1 accumulation." (PMID 24444371, 2014). "Using in vitro cultured cortical neurons and a STZ-induced DM rat model, we found that hyperglycaemia directly induced expression of MAD2B and cyclin B1 accumulation." (PMID 24444371, 2014). "However, the average expression of cyclin B1 did not change significantly in the CRC specimens from the hyperglycemia group (p = 0.2883)." (PMID 30965609, 2019). "However, whether cyclin B1, one substate of APC, is involved in hyperglycaemia-induced cellular injury is still unknown." (PMID 24444371, 2014).
Infertility (4 papers, 2020 to 2025). "Given that change in timing of meiosis reentry and decreased translation of Ccnb1 in oocytes causes infertility, we tested whether a partial loss in CPEB1 expression in oocytes may affect fertility by mating CPEB1+/− female mice with wild-type male mice." (PMID 36697412, 2023). "A study investigating CCNB1 and CCNA2 gene inhibition in mice found that both CCNB1-null and CCNA2-null mice exhibited infertility." (PMID 41153330, 2025). "This search revealed that in the case of NANOS1 overexpression, three infertility related genes (CREBBP, CCNB1, and NPAS2) and five cancer-germ cell genes (CENPL, ERCC6L, KIF18A, SIAH1, and TRIM71) were present in three clusters." (PMID 35743036, 2022).
laryngeal squamous cell carcinoma (4 papers, 2006 to 2025). A squamous cell carcinoma that arises from the larynx. "detected that cyclin B1 elevation may be related to the malignant development of laryngeal squamous cell carcinoma." (PMID 40336533, 2025). "In this study, we analyzed the expression profile of four genes (CCNA2, CCNB1, CCNB2, and CDK1) in laryngeal squamous cell carcinoma (LSCC) cell lines and tumor samples." (PMID 26912061, 2016). "In the current study, we have analyzed the expression pattern of group of genes —CCNB1, CCNB2, CCNA2, and CDK1 in laryngeal squamous cell carcinoma." (PMID 26912061, 2016).
pituitary tumour (4 papers, 2015 to 2023). "Our subsequent research found that suppressing the CCNB1 gene can regulate the proliferation and apoptosis of pituitary tumour cells and activate the epithelial-mesenchymal transition (EMT) process." (PMID 31585531, 2019). "Some studies have shown that CCNB1 can affect the development of pituitary tumours through the cell cycle." (PMID 31585531, 2019). "Using in vivo and in vitro studies, we demonstrated that CCNB1 promotes the migration and invasion of pituitary tumour cells be its involvement in EMT." (PMID 31585531, 2019).
Stroke (4 papers, 2020 to 2024). Sudden impairment of blood flow to a part of the brain due to occlusion or rupture of an artery to the brain.
tongue cancer (4 papers, 2015 to 2023). A malignant neoplasm affecting the tongue. "Specifically, cyclin B1 is significantly upregulated in tongue carcinomas, a subtype of OSCC, and this increased expression is linked to more aggressive characteristics in OSCC." (PMID 38067304, 2023). "Altogether, the aberrant expression of cyclin B1, particularly in tongue carcinomas, provides valuable information about the aggressiveness of the cancer and its potential to spread, aiding diagnosis, prognosis, and treatment decision making in OSCC patients." (PMID 38067304, 2023). "The presence of cyclin B1 has been established as a reliable marker for assessing the degree of tumor proliferation in OSCC and is considered a useful prognostic indicator for predicting lymph node metastasis in tongue carcinomas." (PMID 38067304, 2023).
benign prostatic hyperplasia (3 papers, 2014 to 2024). A non-cancerous nodular enlargement of the prostate gland. "Autoantibodies to cyclin B1 and fourteen other TAAs were detected by enzyme-linked immunosorbent assay (ELISA) and Western blotting in 464 sera from patients with PCa, benign prostatic hyperplasia (BPH), and other controls." (PMID 24860838, 2014). "Regarding the distinction between patients with PC and patients with benign prostate hyperplasia, autoantibodies against cyclin B1 were found present in 31.0% of sera from patients with pancreatic cancer while only in 4.8% of patients with benign prostatic hyperplasia." (PMID 39234247, 2024).
colorectal adenocarcinoma (3 papers, 2012 to 2020). The most common type of colorectal carcinoma. "In LoVo human colorectal adenocarcinoma cells, BBR dose- and time-dependent treatment downregulated cell cycle protein, such as cyclin B1, cdc25c, and cdc2, leading to cell cycle arrest in G2/M phase and suppression of colorectal adenocarcinoma cell growth." (PMID 32855766, 2020). "The expression of cyclin B1, cyclin D1 and cyclin A was decreased by resveratrol in SW480 human colorectal adenocarcinoma cells." (PMID 27007366, 2016).
follicular lymphoma (3 papers, 2006 to 2015). Follicular lymphoma is a form of non-Hodgkin lymphoma characterized by a proliferation of B cells whose nodular structure of follicular architecture is preserved. "A recent study suggests that high expression of cyclin B1 predicts a favourable outcome of patients with follicular lymphoma." (PMID 16420705, 2006).
Insulin resistance (3 papers, 2022 to 2024). Increased resistance towards insulin, that is, diminished effectiveness of insulin in reducing blood glucose levels. "HDL-c is believed to mitigate insulin resistance by counteracting the effects of LDL-C, which reduces the expression of cyclin B1 in pancreatic β-cells and thereby exacerbates insulin resistance." (PMID 39588337, 2024). "In cellular experiments, LDL-C was shown to decrease the expression of cyclin B1 in pancreatic β-cells, resulting in increased insulin resistance, and HDL-C is thought to improve insulin resistance by suppressing the effects of LDL-C." (PMID 37940952, 2023).
invasive breast carcinoma (3 papers, 2009 to 2023). A carcinoma that infiltrates the breast parenchyma. "We analysed cyclin B1 expression on 1348 invasive breast cancers and studied correlations with other histopathological variables and survival." (PMID 19293801, 2009). "The HER2-positive invasive breast cancer samples used for the determination of cyclin B1 expression showed a direct correlation between positive cyclin B1 staining and higher tumor grade, large tumor size, positive lymph node counts, younger age, and higher Ki-67 expression." (PMID 33920506, 2021).
malignant glioma (3 papers, 2002 to 2021). A grade III or grade IV glioma arising from the central nervous system. "Circ-CCNB1 interacts with two key mitosis-related proteins to form a ternary circ-CCNB1-cyclinB1-CDK1 complex in malignant glioma cell lines." (PMID 34745938, 2021). "Altogether, our results indicate that Mxi1 mediates the down-regulation of cyclin B1 gene expression in malignant gliomas suggesting that this gene is a functional target of the tumour suppressor activity of Mxi1." (PMID 11875718, 2002).
medulloblastoma (3 papers, 2017 to 2021). A malignant, invasive embryonal neoplasm arising from the cerebellum. "It has been proven that the expression of LDHB alone was not able to predict a difference in OS, but the concomitant expression of LDHB and CCNB1 was able to identify medulloblastoma patients with a significantly worse prognosis." (PMID 33553434, 2021). "Further, downstream targets of FOXM1 such as PLK1 and cyclin B1 were significantly reduced thus affecting the cell cycle progression in medulloblastoma cell lines." (PMID 31541075, 2019).
pancreatic ductal adenocarcinoma (3 papers, 2016 to 2024). An infiltrating adenocarcinoma that arises from the epithelial cells of the pancreas. "One very recent study conducted in human pancreatic ductal adenocarcinoma cell lines revealed that inhibition of extracellular signal-regulated kinase (ERK) led to dephosphorylation of Cdc20 and concomitant loss of APC/C target proteins securin and cyclin B (CCNB1 and CCNB2)." (PMID 39412391, 2024).
prostate adenocarcinoma (3 papers, 2015 to 2023). "Moreover, miR-744 induces Ccnb1 expression by targeting its promoter, and short-term overexpression of miR-744 resulted in enhanced cell proliferation of mouse prostate adenocarcinoma cells, all of which is indicative of an oncogenic potential." (PMID 25961434, 2015).
Sepsis (3 papers, 2016 to 2024). Sepsis is defined as life-threatening organ dysfunction caused by a dysregulated host response to infection. "We also found that the increased rate of CD4 T cell proliferation in sepsis following treatment with ghrelin was directly linked with the increased expression of cell cycle positive regulators cyclin D1 and cyclin B1 and decreased expression of the cell cycle negative regulator p57." (PMID 30052667, 2018). "Genes including CCNB1, CCNB2 and TOP2A, as well as transcription factors like FOXM1 might be used as the novel gene therapy targets for sepsis related ARDS." (PMID 27090785, 2016).
adenoma (2 papers, 2013 to 2022). A neoplasm arising from the epithelium. "Array data mining found that genes such as Ccnb1, Igfbp3, Nusap1, Pttg1, Racgap1, Top2a, Tpx2, which are associated with the aggressive behaviour of various human tumors, including PAs, and proto-oncogenes such as Ect2, Kit, Kras, Lyn, Ret are up-regulated in rat adenomas." (PMID 23756599, 2013). "Some genes or gene families we found up-regulated in MENX adenomas had previously been identified in human aggressive-invasive PAs, e.g., PTTG1, RACGAP1, CCNB1, CENPE, AURKB." (PMID 23756599, 2013).
bladder tumor (2 papers, 2019 to 2022). "The CCNB1 signature presents a promising diagnostic tool for identifying sufferers with non-invasive bladder tumour with a higher risk of recurrence and predicting responses to IVT." (PMID 31870357, 2019).
bladder urothelial carcinoma (2 papers, 2021 to 2022). "We also explore the predictive value of these six cell cycle related genes and found that CCNB1, CDC20 and CDC25C could also predict the overall survival rate of bladder urothelial carcinoma patients." (PMID 33980246, 2021).
brain tumor (2 papers, 2020). "In addition, other positive regulators that participate in the G2/M transition, such as CDC25C phosphatase and cyclin B1, were downregulated by DMC through inducing reactive oxygen species (ROS) production in brain tumor cells." (PMID 32188144, 2020).
breast adenocarcinoma (2 papers, 2015 to 2023). "The disruption of the CDC2/cyclin B1 complex suggested that SFN may have antitumor effects on established breast adenocarcinoma cells." (PMID 37189614, 2023). "However, beyond chemo-sensitization, cell cycle proteins could serve as targets to inhibit metastasis, since delivering specific siRNAs against survivin and cyclin B1 (with linear PEI) were found to be effective to prevent lung metastasis in a mammary adenocarcinoma model in mice." (PMID 25763370, 2015).
celiac disease (2 papers, 2019 to 2025). An autoimmune genetic disorder with an unknown pattern of inheritance that primarily affects the digestive tract. "However, we also identified a celiac disease specific signature linked to increased cell proliferation, nuclear division, and cell cycle activity that was localized primarily to the epithelia as noted by CCNB1 and Ki67 staining." (PMID 31700112, 2019). "Additionally, studies on celiac disease have shown that CCNB1 is highly expressed in epithelial cells of affected patients, correlating with increased cell proliferation and mitosis, which overlaps with features of CD." (PMID 40406126, 2025).
cervical adenocarcinoma (2 papers, 2013 to 2020). An adenocarcinoma arising from the cervical epithelium. "A previous study reported that pargyline induced cell cycle arrest by the decrease of cyclin B1 protein in human cervical adenocarcinoma HeLa cells." (PMID 23900512, 2013).
chronic myelogenous leukemia (2 papers, 2017 to 2022). "In human chronic myelogenous leukemia cells, a study showed that MP inhibits cell proliferation via G2/M arrest and apoptosis, which are attributed to down-regulation of cyclin B1, Ca2+ homeostatic perturbation, mitochondrial dysfunction, and ROS generation." (PMID 28327651, 2017). "It is displayed that FAM168A might act as a linker protein binding to BCR-ABL1 and AKT1, further enhanced the activity of AKT1/NF-κB signaling pathway, thus, increased of G2/M phase cells and Cyclin B1 level in chronic myeloid leukemia." (PMID 35459265, 2022).
colorectal tumor (2 papers, 2024 to 2025). "Additionally, Chk1-induced CCNB1 overexpression promotes colorectal tumor growth." (PMID 41614789, 2025).
endometrial tumors (2 papers, 2016 to 2020). "When analysing all endometrial tumors in the TCGA data set, a positive correlation with aneuploidy score was observed for both UCHL1 RNA expression and cyclin B1 protein levels." (PMID 31906456, 2020). "In addition, pathway analysis and clustering of the endometrial tumors in the TCGA data set revealed that dysregulation of mitotic processes is a frequent occurrence in USC, including increase in cyclin B1, CDK1 and cyclin E1 protein expression." (PMID 31906456, 2020). "Analysis of the Cancer Genome Atlas (TCGA) database of endometrial tumors identified an inverse correlation between PR and Myc mRNA levels, with a corresponding inverse correlation between PR and Myc downstream transcriptional targets SRD5A1, CDK2 and CCNB1." (PMID 26859414, 2016).
Fanconi anaemia (2 papers, 2013 to 2021).
Hepatic steatosis (2 papers, 2024 to 2026). Steatosis is a term used to denote lipid accumulation within hepatocytes. "In control diet fed mice, Nrf2 deficiency was nonconsequential, while Nrf1 and combined deficiency exacerbated the effect, as demonstrated by hepatic steatosis as well as significant or trending increases in hepatic triglyceride and expression of Ccl2, Ccnb1, Col1a1, Col3a1, Ihh, and Tnfrsf12a." (PMID 39125617, 2024).
liposarcoma (2 papers, 2017 to 2019). A usually painless malignant tumor that arises from adipose tissue.
lymph node metastasis (2 papers, 2015 to 2023). "The poor prognosis and lymph node metastasis for intestinal-type carcinomas were also linked with the expression of Cyclin B1, as both pRB and Cyclin B1 were positive for diffuse carcinomas." (PMID 36769170, 2023). "The results revealed that overall survival was significally related to the Cyclin B1 expression level (RR = 2.062; 95% CI, 1.273–3.340; P = 0.003) and other four parameters (tumor size, lymph node metastasis, distant metastasis, and TNM stage; all P < 0.05)." (PMID 25962181, 2015). "However, Cyclin B1 overexpression was negatively correlated with aggressive clinicopathological features, such as lymph node metastasis, distant metastasis, and TNM stage." (PMID 25962181, 2015). "We further found that the relative mean expression of Cyclin B1 was much lower in patients with lymph node metastasis than that in patients without metastasis (P = 0.011)." (PMID 25962181, 2015).